STAT3 (signal transducer and activator of transcription 3)
Diseases named in the same sentence as STAT3 in open-access papers (continued):
Sharing a sentence is not in itself a finding about the gene and the disease.
Autoimmunity (continued). "In addition, a gain of function mutation of STAT3 leads to impaired erythropoiesis and anemia phenotype, also autoimmunity." (PMID 34177624, 2021). "Importantly, STAT3 gene mutations have been associated with immunodeficiency, autoimmunity, recurring bacterial infections of the skin, increased circulating immunoglobulin E (IgE) and severe eczematoid rash." (PMID 32886659, 2020). "Furthermore, many of the cell populations that STAT3 can induce have been implicated in driving autoimmunity; this includes Tfh cells and B cells, which support autoantibody production and Th9 and Th17 cells, can produce potentially damaging cytokines." (PMID 29472924, 2018). "However, many patients display hypogammaglobulinemia, and thus that autoimmunity in STAT3 GOF seems to be caused by dysregulation of antibody response rather than a general increase of Tfh response." (PMID 30061896, 2018). "That said, the association of aberrant Stat3 activation and autoimmunity has also been recognized." (PMID 28694810, 2017). "However, recent findings implicated many of these proteins in autoimmune disorders, while immuno-regulatory proteins (STAT3, STAT5, NF-κB, NFAT etc.)have been linked to tumorigenesis." (PMID 26246474, 2015). "However, systemic deletion of Stat3 is incompatible with embryonic development, and tissue-specific Stat3 ablation in adult mice triggers enterocolitis, impairs T-cell migration and ultimately causes Th1 autoimmunity." (PMID 20478049, 2010). "For instance, while functional mutations in STAT3 may manifest with lymphoproliferation, including lymphadenopathy and hepatosplenomegaly, and early-onset multisystem autoimmunity, STAT3 loss-of-function mutations underlie hyperimmunoglobulin E syndrome (Job’s syndrome)." (PMID 38644452, 2024). "Similarly, individuals with infantile-onset multisystem autoimmune disease due to dominant gain-of-function STAT3 mutations or common variable immunodeficiency 8 with autoimmunity due to recessively inherited LRBA mutations may present with neonatal diabetes." (PMID 29417186, 2018). "Importantly, targeted disruption of the STAT3 signaling pathway in mice leads to loss of T cell tolerance, highlighting the central role of STAT3 in maintaining peripheral tolerance, and the prevention of autoimmunity." (PMID 24073274, 2013). "Another example is IL-6 that advances cancer cell survival, production, and immune resistance through the activation of STAT3 signaling routes and elicits persistent inflammation and autoimmunity by overproducing IL-6 in autoimmune disorders." (PMID 41465368, 2025). "A gain-of-function (GOF) mutation in STAT3 results in an inborn error of immunity (IEI), characterized by multi-organ autoimmunity and lymphoproliferation." (PMID 40703313, 2025). "PTPRM is reported to dephosphorylate and thereby negatively regulate the activation of STAT3, a crucial transcription factor in the immune system with links to autoimmunity." (PMID 39359478, 2024). "More recently, STAT3 GOF disease has been described primarily in patients with autoimmunity and lymphoproliferation." (PMID 39599507, 2024). "STAT3 GOF is characterized primary by autoimmunity and lymphoproliferation, but recurrent and/or chronic infections do occur in about 75% of patients." (PMID 39599507, 2024). "In conclusion, we identified monozygotic triplets concordant for developmental delay and early-onset autoimmunity to harbor an interstitial 18p deletion including PTPRM–a negative regulator of STAT3." (PMID 39359478, 2024). "Knockdown of miR-155 can alleviate skin damage and inflammatory responses and relieve autoimmunity in CSU rats by inhibiting the JAK/STAT3 signaling pathway." (PMID 38951930, 2024). "Since STAT3 GOF and immunodysregulation polyendocrinopathy enteropathy X-linked (IPEX) syndrome share symptoms such as autoimmunity, together with reduced Treg cell frequency, it is arguable that STAT3 GOF belongs to the spectrum of “Tregopathies”." (PMID 37140667, 2023).
Autoimmunity (continued). "Disruption of the IL-6/IL-6R interaction upstream of STAT3 via the anti-IL-6R monoclonal antibody tocilizumab was shown to partially improve autoimmunity by increasing FoxP3 + Treg cells." (PMID 37702894, 2023). "Nowadays, NETs are considered to have a significant role in the etiology of lupus autoantigens and in driving proinflammatory mechanisms, thus providing a pathomechanistic link between autoimmunity and STAT3 DN in this context." (PMID 37140667, 2023). "Germline gain-of-function (GOF) variants in the signal transducer and activator of transcription 3 (STAT3) gene is an inborn error of immunity presenting with autoimmunity and lymphoproliferation." (PMID 38549698, 2023). "The high rate of concurrent self-reactive autoimmunity and LGL in carriers of STAT3 GOF variants has led to the concept that they develop via similar molecular mechanisms." (PMID 37377909, 2023). "It is worth mentioning that, contrary to the former assumption of only immunodeficiency in STAT3 DN syndrome, recent reports on autoimmunity phenotypes have been published." (PMID 37140667, 2023). "Some studies have consistently reported a critical role of STAT3 in the B cell maturation, differentiation, as well as the autoimmunity." (PMID 35188103, 2022). "Signal transducer and activator of transcription 3 (STAT3) gain-of-function (GOF) mutations cause early-onset immune dysregulation syndrome, characterized by multi-organ autoimmunity and lymphoproliferation." (PMID 35677041, 2022). "Altered phosphorylation of STAT3 in STAT3 deficiency or DNA methylation in DNMT3B and ZBTB24 are probably accounted for the autoimmunity in these diseases." (PMID 36544766, 2022). "STAT3 gain-of-function (GOF) syndrome is a multi-organ primary immune regulatory disorder characterized by early onset autoimmunity." (PMID 36843887, 2022). "STAT3 is essential for the development and function of Th17 cells controlling inflammation or steering autoimmunity." (PMID 36341492, 2022). "Signal Transducers and Activators of Transcription family 3 (STAT3) broadly participates in normal development, the acute phase response, chronic inflammation, autoimmunity, metabolism and cancer progression." (PMID 35488279, 2022). "STAT3 GOF mutations cause early-onset immune dysregulation syndrome, characterized by multi-organ autoimmunity and lymphoproliferation." (PMID 35677041, 2022). "IL-6–/– and IL-23–/– mice are resistant to EAE induction, confirming the critical role of IL-6/IL-23/STAT3 signaling in CNS autoimmunity." (PMID 33411696, 2021). "Both STAT3 GOF and STAT5B deficiency result in impairment of Treg function, which explains the autoimmune manifestations, but how autoimmunity affects the development of ILD needs further study." (PMID 34207510, 2021). "STAT-3 GOF is also featured by an increased risk of severe infections, deriving from a combined immune defect, associated with a high incidence of autoimmunity (cytopenia, enteropathy, endocrinopathy, arthritis)." (PMID 34682853, 2021). "The immunological features of STAT3 GOF mutations included hypogammaglobulinemia, increased Th17 cells and decreased Treg cells, which plays a critical role in the development of autoimmunity." (PMID 33731004, 2021). "Previous studies have illustrated the protective effect of STAT3 on autoimmunity and CVB3-induced myocarditis." (PMID 33658937, 2020). "Tr17 cells are the activated Treg cells that regulate Th17 cell-dependent autoimmunity in a STAT3-dependent manner." (PMID 33362761, 2020). "It should be noted that while a subtle increased STAT3 activation by these newly engineered IL-2Rβ-CAR-T cells was therapeutically beneficial, STAT3 gain-of-function mutants induced multi-organ autoimmunity and large granular lymphocytic leukemia." (PMID 31766350, 2019).
Autoimmunity (continued). "Signal Transducer and Activator of Transcription-3 (STAT3) GOF mutations cause an autosomal dominant disease characterized by early-onset lymphoproliferation, recurrent infections, autoimmunity and, in some cases, growth retardation." (PMID 31440487, 2019). "In order to explore a new therapy for CAU, the current study was performed to investigate the possible functioning of the Oncostatin M receptor (OSMR) gene in the autoimmunity of CAU via regulation of the JAK/STAT3 signaling pathway." (PMID 30134804, 2018). "Thereby, it can be concluded that OSMR gene silencing inhibits autoimmunity in CAU mouse models by inactivating the JAK/STAT3 signaling pathway." (PMID 30134804, 2018). "For instance, while a persistence immune response and autoimmunity would be expected, patients with GOF Stat3 mutations often develop immunodeficiencies and are more susceptible to infections." (PMID 29866996, 2018). "STAT3GOF patients provide a clear demonstration that STAT3 plays an important role in controlling autoimmunity." (PMID 29472924, 2018). "Taken together, these data are consistent with a role for STAT3 in promoting autoimmunity; however, STAT3 is also likely to play a role in inhibiting damaging responses downstream of IL-10." (PMID 29472924, 2018). "In summary, it is shown that a targeting of MST1 in DCs promotes IL-6 along with the expression of IL-6Rα/β and STAT3, thereby contributing to the programming Th17 cell differentiation in the inflammation that arises in both autoimmunity and fungal infection." (PMID 28145433, 2017). "We therefore suggest that sequencing of STAT3 should be considered in more patients with severe autoimmunity, and specified treatment options focusing on the Th17 pathway like tocilizumab should be further explored for these patients." (PMID 26343524, 2015). "This knowledge of the molecular interactions that mediate STAT3 nuclear trafficking is critical to provide a basis to develop strategies to block its action in cancer and autoimmunity." (PMID 21625522, 2011). "For example, abnormally elevated concentrations of IL-6 could possibly saturate the IL-11 receptors, leading to dysregulated STAT3 activation, promoting chronic inflammation and autoimmunity." (PMID 41333011, 2025). "Taken together, we propose that the deletion of PTPRM may contribute to the triplets’ autoimmune manifestations by reducing the negative regulation of STAT3 phosphorylation, thereby increasing Th17 cell fractions and promoting autoimmunity." (PMID 39359478, 2024). "STAT3 gain of function often accompanies autoimmunity and autoinflammation." (PMID 40625455, 2024). "Genetic abnormalities, and in particular STAT3 GOF mutations, which keep lymphocyte activation of T cell clones out of check, have been regarded as one of the putative explanations for the development of autoimmunity." (PMID 38238319, 2024). "Mutations in STAT3 gene has been reported to cause AD-HIES in the setting of a loss of functionality, but dysregulation of the immune system (such as immunodeficiency, malignancy, and autoimmunity) in the setting of a gain of functionality." (PMID 35345674, 2022). "When early-onset ILD accompanied with or without other autoimmunities was encountered in the clinical setting, STAT3 GOF mutation should be considered apart from other congenital pulmonary diseases." (PMID 35677041, 2022). "Therefore, the potentiation of this signaling loop through STAT3 hyperactivation results in decreased differentiation and function of Tregs, likely accounting for autoimmunity in patients with STAT3 gain of function." (PMID 33795850, 2021).
Autoimmunity (continued). "STAT3 is thought to lead to autoimmunity by promoting the activation and expansion of autoimmunity-associated TH17 cells, a subtype of T cell deeply involved in the early mechanisms of autoimmunity." (PMID 34322134, 2021). "It was proved that the hyperactivation of STAT3 may resulted in the occurrence of autoimmunity and immunodeficiency through regulating immune cells." (PMID 34429116, 2021). "STAT3 induces RORγt expression, and was shown to be necessary for the development of Th17 cells and Th17 related autoimmunity, such as seen in RA so EVs inhibiting STAT3 activation could lead to the drop in Th17 polarisation observed." (PMID 35008555, 2021). "Activation in STAT3 may lead to autoimmunity by damaging the development of regulatory T-cells, presumably because of enhanced IL-6 signaling, and stimulating the expansion and activation of TH17 cells." (PMID 33442967, 2021). "Further investigation that analyzes the effects of LLL12b on Th1 differentiation and encephalitogenicity in vitro and in vivo may reveal if STAT3 inhibition may suppress both encephalitogenic populations in CNS autoimmunity." (PMID 33411696, 2021). "The enhanced autoimmunity upon deletion of STAT3 in B cells is also recapitulated in experimental autoimmune encephalitis, a mouse model of multiple sclerosis and thus support our conclusion that STAT3 deletion in B cells enhanced inflammation and the effects observed are not model specific." (PMID 33004854, 2020). "Gain-of-function mutations of STAT3 cause early-onset lymphoproliferative disease and autoimmunity, those of STAT1 lead to chronic mucocutaneous candidiasis, but also autoimmunity, and dominant negative mutations of STAT3 cause a hyper-IgE syndrome, known as Job syndrome." (PMID 31443172, 2019). "In particular, IL-15-induced STAT3 activation could counteract the IL-15-STAT5-mediated NK-cell cytotoxicity to prevent autoimmunity." (PMID 31569642, 2019). "However, more recently it has been appreciated that the opposite, namely STAT3 GOF mutations, can cause early-onset lymphoproliferation and autoimmunity." (PMID 30671054, 2018). "However, previous evidence from other disease states had already indicated that STAT3 played an important role in the regulation of autoimmunity." (PMID 29472924, 2018). "As these LGL leukemias are of either CD8+ T cell or NK cell origin, this suggests that STAT3 overactivation in CD8+ T cells or NK cells alone may be sufficient to drive autoimmunity, possibly by inducing the production of cytokines/inflammatory mediators." (PMID 29472924, 2018). "It is attractive to speculate that IL-15-induced STAT3 activation may serve to counteract the IL-15-STAT5-mediated NK-cell cytotoxicity to prevent autoimmunity." (PMID 28149296, 2016). "Interestingly, STAT3 signaling has been shown to constitute an absolute requirement for pathologic Th17 differentiation and the development of Th17-dependent autoimmunity." (PMID 23383175, 2013). "Of note, genetic abnormalities, particularly STAT3 GOF mutations, have been regarded as a potential molecular mechanism involved in the development of autoimmunity (i.e., cytotoxic T-cell clones have been hypothesized to perpetuate tissue damage both directly and by inducing autoantigens)." (PMID 40191194, 2025). "Other rare monogenic forms of autoimmunity are also instructive including LPS-responsive and beige-like anchor protein (LRBA) deficiency, CD25 deficiency and signal transducer and activator of transcription 3 (STAT3) gain-of-function, all of which impair Treg cell function." (PMID 35979360, 2022). "While DN STAT3 mutations cause STAT3-HIES, the phenotype of GOF mutations varies: somatic mutations are associated with large granular lymphocytic leukemia and germline mutations with a variable syndrome of early-onset multiorgan autoimmunity and lymphoproliferation." (PMID 33932191, 2021).
Autoimmunity (continued). "Notably, STAT3 overexpression significantly reduced the mRNA levels of DC co-stimulatory molecules and MHC molecules, consistent with previous findings that STAT3 is crucial for the tolerant function of DCs and DCs conditional deletion of Stat3 resulted in T-cell activation and autoimmunity in mice." (PMID 34707127, 2021). "Somatic activating gain-of-function (GOF) STAT3 mutations in the SH2 domain have been described in patients with T-lymphocyte and NK- cell Large Granular Cell Leukemia characterized by adult-onset lymphoproliferation, as well as autoimmunity with immune-mediated cytopenias." (PMID 31799221, 2019). "Additionally, the current findings demonstrate that the contents of IL-1, IL-6, IFN-γ and IgE in serum of mice in the OSMR-siRNA group were significantly reduced, indicating that OSMR gene silencing suppressed the autoimmunity of CAU by blocking the JAK/STAT3 signaling pathway." (PMID 30134804, 2018). "The precise timing of STAT3 modulation or inhibiton has not been worked out and it is known that persistent STAT3 ablation may cause autoimmunity in mice." (PMID 28402937, 2017). "In autoimmune disorders such as rheumatoid arthritis, systemic lupus erythematosus, and psoriasis, aberrant activation of the JAK/STAT pathway, especially involving STAT3 and STAT5, is commonly observed." (PMID 41438753, 2025). "The other nodes of the network mainly contain genes/proteins related to autoinflammatory/autoimmunity, such as JAK1, STAT3, STAT5B, IL10RA, and IL10RB, with SOCS3 as a hub." (PMID 39359477, 2024). "Signal transducer and activator of transcription 3 (STAT3) plays key roles in organism development, stem cell proliferation, chronic inflammation, autoimmunity, energy metabolism, and cancer progression." (PMID 36750754, 2023). "RBPs target multiple Th17 cell-related mRNAs such as STAT3, OX40, IL-17 and granulocyte-macrophage colony-stimulating factor (GM-CSF), and contribute to fine-tuning of Th17-dependent autoimmunity and inflammation." (PMID 36599968, 2023). "The low Treg numbers observed in STAT3 GOF are consistent with the role of STAT3 in mediating forkhead box protein 3 (FOXP3)-inhibiting cytokines and concomitant inhibition of differentiation of naïve T cells into autoimmunity-controlling Treg cells." (PMID 37140667, 2023). "This simplistic understanding is outdated and instead a new way of thinking about STAT1, STAT3, STAT6, JAK1, and JAK3 LOF and GOF disease in terms of the relationship between immunodeficiency and autoimmunity is developing." (PMID 37140667, 2023). "Another murine model of STAT3 GOF, reported oligoclonal accumulation of effector CD8+ T cells that contributed to autoimmunity." (PMID 36843887, 2022). "Although the definitive treatment for STAT-related disorders is currently represented by HSCT, the use of JAK inhibitors has demonstrated promising responses in the management of autoimmunity, infections, and lymphoproliferation in STAT1 GOF and STAT3 GOF." (PMID 34682853, 2021). "Moreover, expression of costimulatory molecules was markedly upregulated on CD19-STAT3KO B cells, suggesting that STAT3 attenuates expression of costimulatory molecules on B cells and might thereby serve to restrain excessive activation of T cells that can induce autoimmunity." (PMID 33004854, 2020). "Expression of STAT3 is increased in T cells in SLE, whereas inhibition of STAT3 leads to decreased T cell migration and delayed onset of autoimmunity in lupus prone mice." (PMID 26648939, 2015). "Thus, IL-15/IL-15Rα activates the JAK1/JAK3 and STAT3/STAT5 pathways to induce proliferation of T and NK cells, and this mechanism could limit exposure to circulating IL-15, that contributeS to the risk of autoimmunity." (PMID 22888423, 2012). "The absence of the early-onset autoimmunity, lymphoproliferation, and interstitial lung disease characteristic of the STAT3-GOF syndrome further solidifies the classification of our patient's variant as dominant-negative." (PMID 41458089, 2025).